INS (insulin)
Diseases named in the same sentence as INS in open-access papers (continued):
Sharing a sentence is not in itself a finding about the gene and the disease.
Hypertension (continued). "The disruption in insulin signalling may increase the risk factor of CVS disorders (arteriosclerosis, cardiomyopathy, dyslipidemia, coronary artery disease, and hypertension) and CNS disorders (AD, depression, PD, Schizophrenia, psychosis and epilepsy)." (PMID 38441007, 2024). "In prescribing antioxidants for a complex condition such as MetS, it is not only their antioxidant function that matters, but their other activities, such as their effects on glucose levels, insulin, dyslipidemia, adipose tissue remodeling, and hypertension, should also be considered." (PMID 38892574, 2024). "We were therefore able to analyze whether this relationship changed across age, gender, ethnicity, BMI, smoking status, hypertension and insulin use, assessing the robustness of the relationship." (PMID 39850479, 2024). "In addition, GRK6 regulates insulin homeostasis, an abnormality which participates in the pathogenesis of hypertension." (PMID 38961282, 2024). "Moreover, HIIT has been shown to reduce insulin and blood sugar levels, improve insulin sensitivity, and enhance the mechanisms of blood dynamics, metabolism, and endocrine factors involved in the pathogenesis of hypertension in healthy populations." (PMID 38476670, 2024). "High blood pressure disrupts insulin signaling in two key ways: it damages blood vessels, making insulin delivery more challenging, and, through chronic inflammation, it further weakens the cells’ response to insulin." (PMID 39596023, 2024). "Pain can have several effects on the body’s homeostasis, including the release of catecholamines, leading to cardiovascular and circulatory stress manifested in tachycardia and hypertension, and the release of cortisol, which increases glucagon levels and decreases insulin levels." (PMID 37760305, 2023). "In addition, income, BMI, hypertension, chronic kidney disease, history of cardiovascular disease, insulin use, and duration of DM showed significant interactions." (PMID 37208672, 2023). "Importantly, in the case of concomitant hypertension, the patient will experience further increases in the sympathetic response to insulin, leading to a vicious cycle of continuously increasing blood pressure." (PMID 37583585, 2023). "Changes in peripheral insulin signaling specifically impact neuronal function that leads to neuropathy as well as cardiac complications such as atherosclerosis, hypertension, and heart failure through mechanisms that involve lipid metabolism, inflammation, and oxidative stress." (PMID 37885804, 2023). "When insulin signaling is diminished, as may occur in insulin-resistant states, it may lead to a number of substantial renal complications, including albuminuric glomerular disease and hypertension." (PMID 37887341, 2023). "The results showed that after adjusting for confounding factors (DN, DR, DPN, DF, history of insulin use, history of biguanides use, history of thiazolidines use, history of antihypertensive drugs use, history of hypertension use, ACR, TC, TG, HDL, LDL, eGFR, P, Ca, HbA1c, serum C peptide)." (PMID 38144561, 2023). "Importantly, this association held irrespective of other factors such as age, sex, pre-existing diagnosis of hypertension or other cardiovascular diseases, and the administration of other antidiabetic medications like metformin or insulin." (PMID 37626788, 2023). "In addition, age, triglyceride level, and the prevalence of hypertension and insulin use differed significantly according to the quartiles of urinary albumin excretion." (PMID 37916147, 2023). "Furthermore, among patients with hypertension, those taking medication in the form of a pill were more willing to receive mobile phone–based health services than those taking injectable insulin." (PMID 36917174, 2023).
Hypertension (continued). "Additionally, at follow-up, the HA-HA and HA-NA groups exhibited higher blood pressure, a higher prevalence of hypertension, elevated serum triglycerides and insulin levels, and lower levels of HDL cholesterol compared to the NA-NA group." (PMID 37629271, 2023). "Insulin resistance (IR) is a clinical state of impaired insulin sensitivity which could result in cardiometabolic alterations, including hyperglycemia, dyslipidemia, and hypertension." (PMID 36864455, 2023). "Furthermore, people with seborrheic dermatitis (SED) and rosacea are more prone to insulin resistance, high blood pressure (BP), and higher blood lipids." (PMID 37752973, 2023). "As a result, the body’s fluid volume increases, blood vessels lose some of their elasticity, and insulin resistance may increase the chance of developing high blood pressure." (PMID 37244992, 2023). "Thus, patients with T2DM exhibit impaired endothelium-dependent flow-mediated dilation (FMD), as well as insulin-mediated NO-dependent vasodilation and hypertension." (PMID 37445602, 2023). "Second, several adipose tissue-derived factors may influence insulin signaling, thereby affecting insulin-mediated vasodilation, ultimately leading to hypertension." (PMID 35565750, 2022). "Among the clinical parameters, type of diabetes, number of daily insulin injections, ability to describe the insulin regimen, frequency of self-measurement of blood glucose levels and hypertension all showed statistical significance toward insulin adherence in univariate research." (PMID 35573427, 2022). "Age, poverty income ratio, smoking status, hypertension, hyperlipidemia, anti-inflammation therapy, metformin use, insulin use, ARB use, SBP, DBP, SII, glycohemoglobin, Scr, BUN, SUA, eGFR, TG, ACR, ASCVD, and CHF were significantly different between the two groups (all p<0.05)." (PMID 36561561, 2022). "The potential health benefits of lupine (seeds), including energy metabolism, cardiovascular diseases, hypertension, glucose and insulin metabolism, bower function and anticonvulsant action, are discussed based on scientific evidence (both clinical trials and studies performed with animal models)." (PMID 36500649, 2022). "The analysis was adjusted for insulin, metformin, anti-hypertensive treatment, drinking, smoking, BMI, hypertension, diabetic duration, age, gender, ALT, AST, GGT, WBC, NEU, LYM, NLR, hs-CRP, FFA, TC, TG, HDL-C, LDL-C, Urea, Cr, HbA1c, FPG, 2hPG, GA, GA/ALB, UA and eGFR." (PMID 35842724, 2022). "Therefore, in recent years, the concept of prevention and treatment of hypertension has undergone great changes, lowering blood pressure while improving insulin resistance has become a new approach to treating hypertension." (PMID 36246058, 2022). "In addition, they had a higher prevalence of CVD, hypertension, and cancer; more daily intake of folic acids from food; and higher HbA1c, insulin, HOMA-IR, fasting glucose, and CRP levels; and lower blood vitamin B12 and eGFR levels." (PMID 35548409, 2022). "Circulating insulin level is elevated in subjects with hypertension." (PMID 36479179, 2022). "Next to the local treatment of lung diseases, the inhalative application route, e.g. for insulin therapy or against hypertension, has various advantages, as a faster treatment, higher efficacy and a reduced systemic side effect than other ways of administration." (PMID 38624975, 2022). "Additionally, the literature advocates that hypogonadism is associated with important cardiovascular risk factors, such as general and visceral obesity, impaired insulin sensibility, hypertension, and dyslipidemia." (PMID 35448486, 2022). "During IR, insulin augments the renal sodium reabsorption and provokes sympathetic nervous system work, which could significantly subsidize the blooming of hypertension." (PMID 36111327, 2022).
Hypertension (continued). "First, because no insulin level test was performed, we were unable to measure the degree of IR, which was also considered as a potential risk factor for hypertension." (PMID 36035963, 2022). "Increased age (p = 0.02), insulin use (p = 0.01), hypertension (p < 0.01), and ischemic heart disease (p < 0.01) were associated with significantly decreased estimated glomerular filtration rates (eGFRs) in patients with diabetic retinopathy after 1-year follow-up." (PMID 36361175, 2022). "Several mechanisms may lead to hypertension, such as insulin and leptin resistance, perivascular adipose tissue dysfunction, renal impairment, renin-angiotensin-aldosterone activation, and sympathetic nervous system activity." (PMID 36348493, 2022). "Obesity has serious effects on life expectancy and quality of life, including hyperinsulinemia (high insulin levels), hypertension (high blood pressure) and dyslipidemia (abnormal lipid levels), which can cause heart disease, diabetes, cancer, hypertension and kidney diseases." (PMID 35883978, 2022). "Possibly, altered targeting of IRAP contributes to hypertension in insulin-resistant individuals." (PMID 36246906, 2022). "Thus, we identified two kinds of diabetic patients with differences in their drug therapy (insulin and non-insulin dependant), and also a group of women affected by hypertension and gestational diabetes." (PMID 36064616, 2022). "Univariate analysis demonstrated that the following factors were associated with the presence of CAD: age; gender; glucose metabolism status; hypertension; eGFR; UA; single antiplatelet therapy; use of statin, insulin, and other hypoglycemic drugs; TG/HDL-C ratio; TyG index; and METS-IR." (PMID 35966520, 2022). "The results show that hypertension (a OR=2.41; 95%CI: 1.11-5.22, p=0.026), hypolipidemia treatment (aOR=2.20; 95%CI: 1.06-4.59, p=0.034), insulin use (aOR=0.39; 95%CI: 0.15-0.96, p=0.043) and LDL-C level (aOR=1.01; 95%CI: 1-1.02, p=0.035) are independent risk factors for CVDs in T2DM in this study." (PMID 35655685, 2022). "Therefore, accumulation of bacterial DNA in tissues apparently contributes to high blood pressure and decrease insulin sensitivity in aging WT mice." (PMID 36440192, 2022). "Approximately 20 years lapsed before this topic ended up again in the spotlight and many research groups could provide evidence that resistance to insulin-mediated glucose disposal is highly prevalent in patients with essential hypertension." (PMID 36289636, 2022). "Results from multiple regression models showed that the rates of BCVA, CMT and IOP were significantly modified by sex, DM duration, insulin use, HbA1C levels, hypertension (HTN); this combinations yielded R2 100% (Coefficients 0.0226399, -0.2665421, 0.0804644; P = 0.0083) S2A–S2C Fig." (PMID 33434220, 2021). "The development of hypertension can also result in the worsening of IR through changes in the structure of the vasculature and the impairment of vasodilation within skeletal muscle, with the reduced delivery of glucose and insulin to skeletal muscle cells." (PMID 33430419, 2021). "Therefore, when analyzing several metabolic indicators (i.e., BMI, fasting glucose level, fasting insulin level, and hypertension), we chose a random-effects model to obtain a wider confidence interval and relatively reliable conclusions." (PMID 34660805, 2021). "Additionally, the melanocortin system is an important mediator of the leptin- and insulin-induced forms of hypertension." (PMID 34512392, 2021). "Several studies have concluded that individuals with mutations in the apoCIII gene, which results in life-long lower levels of the apolipoprotein, are healthier with a favorable pattern of lipoproteins, increased insulin sensitivity, lower incidence of hypertension and they live longer." (PMID 33477763, 2021). "Additionally, this leads to hypertension and vascular dysfunction along with dysregulation of glucose/insulin homeostasis in offspring." (PMID 34368253, 2021).
Hypertension (continued). "From many studies on the treatment of hypertension with antihypertensive drugs, it can be speculated that one of their antihypertensive mechanisms is to improve insulin resistance." (PMID 33570444, 2021). "There is growing evidence about the role of altered gut microbiota to promote CVD via several mechanisms, such as altering lipid metabolism, playing a role in vascular dysfunction and hypertension, increasing systemic inflammation, foam cell formation and insulin resistance." (PMID 34277985, 2021). "Logistic regression analysis with enter selection showed that insulin therapy was closely correlated with development of GH (OR = 6.33; 95 %CI, 1.17 to 34.09 vs. the lifestyle intervention, P = 0.032) corrected by history of hypertension, 2 h BG and total GWG." (PMID 34579668, 2021). "Current medication consists of metformin, insulin, and an unknown medication for arterial hypertension." (PMID 34946818, 2021). "As expected, T2 and T3 participants had higher HbA1c, waist circumference, BP levels, and prevalence of hypertension, dyslipidaemia, and treatment with insulin, alone or combined with non-insulin agents, anti-hypertensive drugs, RAS blockers, and lipid-lowering agents." (PMID 33715620, 2021). "This implied that the endothelial dysfunction in response to insulin could play an important role in the development of aging-related hypertension." (PMID 34203897, 2021). "The authors concluded that the best approach to lengthening the lifespan, as well as maintaining good health in old age, would be a multi-targeted approach that includes avoidance of smoking and hypertension and maintaining or enhancing insulin sensitivity and lean body mass." (PMID 34884408, 2021). "In addition, the trigger of autonomic nervous system imbalance by particulate matter which can promote to vasoconstriction, contributes to hypertension and impaired insulin sensitivity." (PMID 33068582, 2021). "In addition, sleep deprivation was found to exert detrimental effects via altering glucose metabolism, decreasing insulin sensitivity and increasing hypertension." (PMID 33479186, 2021). "Our study revealed that for treating hypertension in insulin-treated patients, ACEI or ARB might be more adequate than diuretics." (PMID 33602190, 2021). "Many anthropometric and biochemical markers have been investigated, including BMI, body adiposity index (BAI), waist circumference and waist-to-hip ratio, waist-to-height ratio, high blood pressure, triglyceride levels, insulin and proinsulin levels, and proinsulin-to-insulin ratio (P/I ratio)." (PMID 33723361, 2021). "They revealed that neither insulin nor oral medicines affected the risk of PE development, but insulin significantly increased the incidence of hypertensive disease of pregnancy." (PMID 34202343, 2021). "In addition, the highest hesperidin dose also improved insulin sensitivity, hypertension, and markers of arterial stiffness and inflammation." (PMID 31963315, 2020). "Also, the hypertension disease of T2D reflects insulin-responsive sympathetic activity, renal sodium reabsorption and endothelial vasoconstriction." (PMID 32128655, 2020). "However, amlodipine and enalapril demonstrated to have similar effect on insulin sensitivity using euglycemic hyperinsulinemic clamp in patients with mild to moderate hypertension." (PMID 32258163, 2020). "In addition to insulin use and hypertension, increased HbAlc and decreased plasma sLRP1 levels were the risk factors for MCI in patients with T2DM." (PMID 33013281, 2020). "Therefore, our study aimed to systematically evaluate the efficacy of QDD on blood pressure, life quality, renal function, insulin resistance, and other aspects of patients with hypertension as well as the potential hypertensive mechanism." (PMID 32802140, 2020).
Hypertension (continued). "In particular, low magnesium seem to be associated with increased cardiovascular mortality and the proposed mechanisms include promoting hypertension, cardiac arrhythmias, cardiac remodeling / fibrosis, oxidative stress, insulin resistance and arterial stiffening." (PMID 32050924, 2020). "Current hypotheses suggest that there is a link between hypertension control and alterations in insulin sensitivity, autonomic nervous system function and vasoconstriction regulation." (PMID 32631300, 2020). "However, this program provided more comprehensive services, including insulin and hypertension treatment." (PMID 33361237, 2020). "Experimental animal studies using an insulin-resistant rat model showed that six-week treatments with O. europea extracts prevented the development of hypertension and atherosclerosis, demonstrating the potential of this medicinal plant in the management of hypertension in the African population." (PMID 32526850, 2020). "Cardiovascular insulin effects are reduced in states of insulin resistance and this may contribute to the development of hypertension and and other the cardiovascular complications." (PMID 32093229, 2020). "Furthermore, fructose-fed animals have been shown to develop high blood pressure, fatty liver, high serum triglycerides, and insulin resistance as compared to the control group." (PMID 32599713, 2020). "We hypothesize that failure of suppression of aldosterone and AngII by salt intake together with the antinatriuretic effect of insulin may provide a mechanism for development of essential hypertension." (PMID 32257423, 2020). "It has been reported that about 50% of patients with essential hypertension are insulin resistant." (PMID 32235782, 2020). "Although their model demonstrated good fit according to standard criteria, glucose loaded weakly onto the insulin resistance factor, and hypertension had the weakest loading onto the overall metabolic factor, suggesting that the model may be improved." (PMID 30120425, 2019). "Another novel KD GNB1 in “Insulin regulation” encodes a G protein β subunit, multiple mutations of which were found to affect the protein interface that binds Gα subunits (GNAS), which has been genetically and clinically associated with hypertension." (PMID 30931314, 2019). "Insulin signaling pathways stimulate inflammation and lead to aberrant excessive and uncontrolled endothelial growth resulting in endothelial dysfunction and hypertension." (PMID 31695458, 2019). "Human soluble epoxide hydrolase (hsEH) is an enzyme responsible for the inactivation of bioactive epoxy fatty acids, and its inhibition is emerging as a promising therapeutical strategy to target hypertension, cardiovascular disease, pain and insulin sensitivity." (PMID 31123712, 2019). "The higher impact of IR in the development of hypertension among women, might be attributable to the effect of lower lean body mass in women; hence, fasting insulin or HOMA-IR values in women reflect a higher level of tissue IR." (PMID 30858870, 2019). "Researchers from the community-based Multi-Ethnic Study of Atherosclerosis suggested that higher concentrations of insulin may contribute to the development of hypertension, in part through kidney disease and arterial stiffness." (PMID 31728151, 2019). "Additionally, FGF 23 levels were compared between the subgroups of patients after hypertensive children were sub-grouped according to their cardiac geometry, hypertension stages, insulin levels, and weight." (PMID 31058117, 2019). "In obese subjects, several mechanisms may lead to hypertension such as insulin and leptin resistance, perivascular adipose tissue dysfunction, renal impairment, renin-angiotensin-aldosterone-system activation and sympathetic nervous system activity." (PMID 31330870, 2019).